TLR4 (toll like receptor 4)
Diseases named in the same sentence as TLR4 in open-access papers (continued):
Sharing a sentence is not in itself a finding about the gene and the disease.
schizophrenia (continued). "Higher TLR4/NF-κB signaling in the brain has been related to the generation of subtle neuroinflammation and neural degeneration, contributing to the pathogenesis of schizophrenia." (PMID 36051545, 2022). "This might suggest that some degree of increased TLR4 expression by leukocytes is inherent to schizophrenia." (PMID 35027554, 2022). "Our study revealed that there were important correlations between TLR4 signaling pathway and cognitive function, white matter FA, and there was also a correlation between white matter FA and cognitive performance in stable chronic schizophrenia, respectively." (PMID 36051545, 2022). "The comparison of TLR4 signaling pathway activity in schizophrenia patients and controls." (PMID 36051545, 2022). "We speculated that higher TLR4/NF-κB/IL-1β signaling may compensate for functional deficits of monocytes and, as a result, less increases in monocytic TLR4 levels upon LPS stimulation in schizophrenia." (PMID 36051545, 2022). "TLR4 stimulation resulted in lower pro-inflammatory cytokine production in schizophrenia compared to the control levels, whereas the stimulation of ErbB by neuregulin 1 led to higher pro-inflammatory cytokine levels in patients with schizophrenia relative to the control group." (PMID 28646138, 2017). "The authors suggested that APs might normalize TLR4 expression in persons with schizophrenia." (PMID 40153412, 2025). "Higher monocytic TLR4 expression in people with schizophrenia may contribute to neuroinflammation." (PMID 40153412, 2025). "Furthermore, the activation of the TLR4 pathway in microglia contributes to excessive synaptic pruning, which may play a role in the onset of schizophrenia." (PMID 40242178, 2025). "Furthermore, monocytic TLR4 expressions were inversely correlated with cognitive function and white matter FA, but not with cortical thickness or subcortical gray matter volume in schizophrenia." (PMID 36051545, 2022). "Therefore, we speculated that there is a potentially etiological relationship between TLR4 signaling activity dysfunction and white-matter deficit in patients with schizophrenia." (PMID 36051545, 2022). "If schizophrenia patients have reduced ACh release due to dysfunction of the sympathetic or parasympathetic nervous system, this pathway could be down-regulated and lead to increased membrane expression of TLR4." (PMID 35844244, 2022). "Thus, a blockade of the TLR4 signaling pathway may represent a novel therapeutic strategy for modulating cognitive performance in schizophrenia." (PMID 36051545, 2022). "However, this raises the interesting question of what else may be inducing increased innate immune receptor TLR4 mRNA in white blood cells in schizophrenia, with the possibility that there may be a higher bacterial load." (PMID 35027554, 2022). "Our finding of schizophrenia-specific relative suppression of TLR4 transcript plausibly reflects microglial quiescence in patients that is not seen in inflamed non-schizophrenic controls, and may reflect a more chronic neuroinflammatory environment in people with schizophrenia." (PMID 32680547, 2020). "The authors concluded that persons with schizophrenia exhibit weakened monocytic TLR4 activation, as indicated by a lower stimulated MFI in persons with schizophrenia, despite similar basal monocytic TLR4 density between the two groups." (PMID 40153412, 2025). "In contrast, whole blood stimulation studies in schizophrenia showed elevated concentrations of IL-6, TNF-α, and IL-1β post-TLR2 stimulation, and increased IL-1β alone post-TLR4 and 8 stimulation." (PMID 37627253, 2023). "In schizophrenia, increased TLR-3 and TLR-4 expression are observed on unstimulated monocytes and associated with an early age of onset." (PMID 36688057, 2022). "In the case of TLR4 stimulation, there were significantly weaker IL-1β, IL-6, and TNF-α responses in schizophrenia relative to the control subjects (p < 0.01), whereas IL-10 production was intact (p > 0.5)." (PMID 28646138, 2017).
schizophrenia (continued). "Results revealed increased TLR4/TLR5 and decreased ErbB4 expression in schizophrenia relative to the control subjects." (PMID 28646138, 2017). "We observed an overall trend toward increased monocytic TLR4 density in persons with schizophrenia (regardless of AP status) compared to HCs, although the difference was not significant." (PMID 40153412, 2025). "Despite recent investigations, a comprehensive understanding of how TLR4 contributes to schizophrenia has not been achieved." (PMID 40153412, 2025). "The overall analysis indicated a pooled effect size of 0.235 (95% CI: –0.245 to 0.715), reflecting a generally nonsignificant increase in TLR4+ monocytes in patients with schizophrenia compared to HCs." (PMID 40153412, 2025). "The overall pooled effect size of 0.317 (95% CI: -0.060 to 0.694) indicated a nonsignificant trend toward greater TLR4 density in individuals with schizophrenia." (PMID 40153412, 2025). "The AP-free subgroup had a combined effect size of 0.399 (95% CI: -0.909 to 1.707), indicating a nonsignificant increase in TLR4+ monocytes in patients with schizophrenia." (PMID 40153412, 2025). "Overall, leukocyte expression of the NF-κB-activating receptors, TLR4 and TNFR2, and the NF-κB subunit, RelB, was increased in people with schizophrenia compared to healthy control subjects (all p < 0.01), while NF-κB-inducing kinase mRNAs IKKβ and NIK were downregulated in patients (all p < 0.05)." (PMID 35027554, 2022). "Currently, the correlations between TLR4 levels and cognitive performance in schizophrenia have not been fully elucidated, with complex and less than consistent results." (PMID 36051545, 2022). "In addition to TLR4, activation of maternal TLR3, a viral receptor, resulted in altered behaviors including schizophrenia-like behaviors, deficit in exploratory and social behavior." (PMID 27445700, 2016). "Additionally, there were nonsignificant tendencies toward elevated NF-κB and TLR4 in individuals with schizophrenia." (PMID 40153412, 2025). "First, the “leaky gut” hypothesis of schizophrenia suggests that gram-negative bacteria can enter the blood due to increased intestinal permeability, resulting in TLR4 signaling pathway activation." (PMID 40153412, 2025). "In schizophrenia, immune activation upregulates pro-inflammatory cytokines (e.g., IFN-γ, IL-1, TNF-α), which activate indoleamine 2,3-dioxygenase (IDO) via both IFN-γ receptor (IFN-γR)-dependent and independent pathways (e.g., synergistic action of TLR4, IL-1R, TNF-αR)." (PMID 41346597, 2025). "Therefore, we speculated that the TLR4 signaling system rarely affects dopaminergic neurons in chronic stable schizophrenia, which may explain our lack of correlation between TLR4 levels and psychopathological symptoms." (PMID 36051545, 2022). "Given that TLR4 is a potent activator of NF-κB and pro-inflammatory microglia, its putative suppression in the cortex in schizophrenia suggests that the increase in cytokines may not be microglia-derived and bolsters the theory of possible microglial suppression in a subset of patients." (PMID 34650030, 2021). "Recently, we demonstrated up-regulated TLR4 and TLR5 on monocytes and lymphocytes of drug-naïve schizophrenia patients; TLR4, but not TLR5, alterations were normalized by antipsychotic treatment." (PMID 28646138, 2017).
acute respiratory distress syndrome (26 papers, 2012 to 2025). Progressive and life-threatening pulmonary distress in the absence of an underlying pulmonary condition, usually following major trauma or surgery. "For example, oxidised phospholipids are agonists for TLR4 and stimulation of TLR4 was associated with acute respiratory distress syndrome in experimental mouse models for acute lung injury, and TLR4 promotes a strong cytokine release by human alveolar macrophages in vitro." (PMID 34995294, 2022). "Furthermore, TLR4-deficient mice were less susceptible to acute respiratory distress syndrome (ARDS) upon inhalation trauma." (PMID 33557133, 2021). "Further to this, it has been mentioned that GL has a protective effect against TLR4 activator LPS-induced acute respiratory distress syndrome (ARDS) in mice." (PMID 34961070, 2021). "In summary, our study confirmed that SYQP induced bidirectional immunity and ameliorated LPS-induced acute respiratory distress syndrome in mice through TLR2/TLR4-NF-κB, NLRP3/caspase and JAK/STAT signaling pathways, which provided a theoretical basis for further use of SYQP." (PMID 35370633, 2022). "In addition to attachment and infection, the S protein–TLR4 interaction is known to promote macrophage activation syndrome, acute respiratory distress syndrome, and cytokine storm leading to multi-organ damage." (PMID 35082779, 2021). "In a mouse model of acute respiratory distress syndrome (ARDS), TLR4 signaling was found to promote neutrophil apoptosis and to attenuate pulmonary inflammation through IFN-β-mediated upregulation of TRAIL." (PMID 24709704, 2013). "This study discusses the anti-inflammatory mechanism of Yiqi Huayu Jiedu decoction (YQHYJD) and studies the intervening effect of YQHYJD on the inflammatory cytokines in acute respiratory distress syndrome (ARDS) rats by inhibiting the TLR4/NLRP3 signal pathway." (PMID 35222667, 2022). "For example, in a lipopolysaccharide (LPS)-induced murine model of acute respiratory distress syndrome (ARDS), alveolar macrophages undergo a TLR4-mediated phenotypic transition from CD11blow to CD11bhigh, thereby enhancing the inflammatory response to pathogens." (PMID 41293166, 2025). "Similarly, infection with highly pathogenic influenza virus induces an acute lung injury, leading to acute respiratory distress syndrome (ARDS), which is mediated through TLR4 signaling as a key disease pathway." (PMID 27891512, 2016). "In LPS and polyinosinic:polycytidylic acid (POLY I:C)-induced acute lung injury (ALI)/acute respiratory distress syndrome (ARDS) models, CGA counteracts the inflammatory and oxidative stress in human airway epithelial cells and in BALB/c mice through targeting the TLR4/TLR3/NLRP3 inflammasome axis." (PMID 38612964, 2024). "Therefore, TLR4 and its subsequent downstream pathway may be of critical importance in SARS-CoV-2 induced acute respiratory distress syndrome and subsequent mortality, even though SARS-CoV-2 does not directly bind to TLR4." (PMID 34995294, 2022).
hemorrhage (26 papers, 2009 to 2023). Loss of blood from the vascular compartment to the exterior or into nonvascular body space as a result of rupture or severance of the blood vessels. "The second model is the gut microbiota theory (LPS-activated Toll-like receptor 4 to induce inflammatory-associated hemorrhage) which focuses on the importance of gut microbiota inducing systemic inflammation that promotes detrimental effects on the BBB." (PMID 36077089, 2022). "A recent study proved that TLR4-dependent inflammation leading to CSF hypersecretion plays a role in the development of hydrocephalus after hemorrhage." (PMID 35729645, 2022). "In conclusion, these studies demonstrate multiple novel findings while reinforcing prior conclusions regarding the complex role of TLR4 and type 17 immune responses following trauma/hemorrhage." (PMID 35663944, 2022). "Inhibition of TLR4-driven inflammation, which is a major mortality factor in trauma–hemorrhage patients, showed positive results in overcoming hemorrhage-induced cardiac dysfunction in vivo." (PMID 36678520, 2022). "Fibrinogen within the clots after ICH is also critical for activation of TLR4 on platelets or leukocytes within the hemorrhage, which contributes to poor outcome after ICH." (PMID 23414417, 2013). "In animal models of adult ICH, TLR-4 protein and mRNA expression peak at three days after hemorrhage and can be detected in neurons, astrocytes and, predominantly, in microglia." (PMID 23915174, 2013). "The TLR4 protein, detected by immunohistochemistry, was consistently distributed in peri-hemorrhage areas, the hippocampus, cortex, thalamic nuclei, and some white matter tracts." (PMID 20150961, 2009). "Such TLR7 activation rapidly induced gastrointestinal hemorrhage and illness in mice, confirming that activation of other TLRs could drive pathology independently of TLR4-signaling." (PMID 35871233, 2023). "al. studied the relationship of TLR4 in mediating lung injuries following HS/R and hypothesized that TLR4 is needed for both the hemorrhagic shock and LPS-induced lung injury." (PMID 25309129, 2014). "Subarachnoid hemorrhage was induced in TLR4−/−, TRIF−/−, MyD88−/− and wild type C57BL/6 mice by injecting 60 μl of autologous blood near the mesencephalon; animals were euthanized 1 to 15 days after SAH for immunohistochemical analysis to detect microglia or apoptotic cells." (PMID 23849248, 2013). "In addition, since we found that TLR4 might be the receptor through which NS1 activates platelets, we used TLR4 knockout mice (TLR4-/-) to investigate the role of TLR4 in DENV-induced hemorrhage in mice." (PMID 31009511, 2019). "Second, the extent of TLR4 downregulation might be accentuated by other factors in addition to bone component exposure because an additive or synergistic effect on immune-suppression has been proven among fracture itself, soft tissue injury, and hemorrhage." (PMID 26273144, 2015). "In the present study, CCMSympt patients (87% with lesional hemorrhage and 13% with seizure crisis) had a higher frequency of (CD4+ and CD8+) T lymphocytes expressing TLR4 gated in a region containing larger and more granular cells than CCMAsympt patients." (PMID 35109870, 2022). "MetHb is an endogenous ligand of toll-like receptor 2 (TLR2) and toll-like receptor 4 (TLR4) that induces pro-inflammatory cytokine and tumor necrosis factor α (TNF-α) production after hemorrhage." (PMID 31357546, 2019).
lung diseases (26 papers, 2005 to 2025). "Given that dysregulation of TLR4 signaling in DCs can lead to a range of immune dysfunctions that contribute to various pulmonary diseases, it is essential to explore these underlying mechanisms in greater detail to identify new targets for treatment." (PMID 39238498, 2024). "Our study indicated that golden buckwheat as a source of functional food prevents or treats associated lung diseases by modulating the activation of the TLR4/NLRP3 signaling pathway." (PMID 39139945, 2024). "Gal3 binds to and activates TREM2 and TLR4, both of which have been associated with pulmonary disease, including fibrosis." (PMID 35069217, 2021). "Decreased levels of SP-A, but increased expression levels of TLR4 are associated with lung diseases, including lung infection and inflammation." (PMID 32576172, 2020). "Among the cellular factors that regulate IAV-induced lung disease, TLR4 is a major contributor to susceptibility and exacerbated pathophysiology associated with IAV infection." (PMID 24391503, 2014). "Thus, targeting TLR4 appears to be an approach to tackle lung diseases from multiple causes." (PMID 24167596, 2013). "Since the clinical application and efficacy of immunotherapies for these diseases present quite limited by far, improved understanding of the role of TLR4 in airway DC activation is helpful for the innovation of promising strategy for these pulmonary diseases." (PMID 39238498, 2024). "Although F2TCDD and F2TCDD/Form pups frequently exhibited new BPD, paternal fish oil supplementation attenuated the expression of pulmonary inflammation (Cxcr2, Il-1 alpha, and Tlr4) and significantly reduced the incidence of lung disease in offspring." (PMID 36976210, 2023). "Gal3 binds and activates TLR4 and TREM2, a process associated with lung diseases and pulmonary fibrosis." (PMID 35069217, 2021). "Previous studies indicated that activation of the TLR4/NF-κB pathway was critical for the pathogenesis of multiple lung diseases, such as ALI." (PMID 33506105, 2020). "As a consequence, S100A9/TLR4 activity exacerbates lung disease by promoting a pro-inflammatory response and inducing cell-death." (PMID 24391503, 2014). "For example, although TLR4 is activated during IAV infection, studies with TLR4 KO mice have shown that TLR4 contributes to exacerbated lung disease and mortality in IAV-infected animals." (PMID 24391503, 2014). "Furthermore, Cynanchum paniculatum and paeonol in pulmonary diseases, at least in part by the inhibition of Toll-like receptor 4 (TLR4)/NF-κB inflammatory signaling." (PMID 32774428, 2020). "We have previously shown that intranasal MHV-1 infection of C3H/HeJ mice, which harbor a natural mutation in the gene that encodes toll-like receptor 4 (TLR4), results in increased morbidity and mortality along with severe pulmonary disease as compared to the wild-type C3H/HeN mice." (PMID 24608125, 2014). "TLR4 is activated during IAV infection and reduced mortality and diminished lung disease (and inflammation) was observed in IAV infected TLR4 KO mice." (PMID 24391503, 2014). "Furthermore, malondialdehyde levels are positively correlated with increased expression of Toll-like receptor 4 (TLR4) and factor nuclear kappa B (NF-κB)—signaling pathways involved in lung diseases." (PMID 33628371, 2021). "Tracheobronchial epithelial cells (TBEC) and AMs from four smokers and four non-smokers without lung disease were cultured with or without Poly(I:C) (PIC) (a TLR3 agonist) or LPS (a TLR4 agonist) for 4, 24 and 48 h." (PMID 29940963, 2018). "Furthermore, in our in vivo experiments, LPS-mediated TLR4 signaling in iNKT cells enhanced IFN-γ production but reduced IL-4 levels in the lungs of mice with HP or BIPF, resulting in the regulation of these pulmonary diseases." (PMID 23028952, 2012).
lung diseases (continued). "There was a trend towards a significant positive correlation between the percentage of TLR4+ non-classical monocytes and c-reactive protein levels (Rho = 0.457, P = 0.075) and the VAS of pulmonary disease activity (0.52, P = 0.006)." (PMID 32164729, 2020).